LGALS9 (galectin 9)
Diseases named in the same sentence as LGALS9 in open-access papers (continued):
Sharing a sentence is not in itself a finding about the gene and the disease.
tumor (continued). "Furthermore, we found a significant positive correlation between tumor purity and promoter methylation (HAVCR2: beads 1–2, LGALS9: beads 7–12) and inverse correlations between tumor purity and mRNA expression as well as gene body methylation (HAVCR2: beads 5–6, LGALS9: bead 13)." (PMID 31747929, 2019). "Galectin-9 directly activates apoptotic cell deaths to these cell lines in vitro, not via activation of tumor immunity, demonstrating that the intracellular mechanisms of apoptosis vary depending on cell lines and that apoptosis common pathways have not previously been established." (PMID 28045432, 2017). "As TIM-3 blockade attenuated galectin-9 induced apoptosis of tumor-infiltrating CD8+ T cells in vitro, we then tested whether this attenuation of apoptosis could be translated into improved tumor inhibition in vivo." (PMID 26493689, 2015). "Tumor galectin-9 expression might be related to HPV infection, as different viruses including human cytomegalovirus, HIV and influenza virus have been shown to induce galectin-9 expression." (PMID 26066796, 2015). "Moreover, LGALS9‐HAVCR2 (Galectin‐9‐TIM‐3) serves as a pivotal regulator of T cell exhaustion, with elevated TIM‐3 expression in various malignancies strongly correlating with poor prognosis and functional exhaustion of CD8+ tumor‐infiltrating lymphocytes (TILs)." (PMID 40891683, 2025). "In addition, the expression of Galectin-9 was also detected in multiple types of B cells, which may include normal and malignant cells, revealing the complex network between tumor cells and background cells, and further suggesting the significance of TIM3/Galectin-9 pathway in DLBCL." (PMID 38369502, 2024). "It is possible that the internalization of Tim-3 induced by the receptor recognition of galectin-9, which is highly expressed by MCF-7 spheroids, may be a reason for the decreased Tim-3 level in pNK cells after interaction with MCF-7 cells compared to that in other tumor cell spheroids." (PMID 39457710, 2024). "We investigated the expression of HAVCR2 and LGALS9, typical immune suppressive genes, and CD163, an M2 macrophage marker gene, and found that they were co-expressed in the macrophage clusters, indicating that the TAMs infiltrating the tumor might be M2 subtype." (PMID 39474422, 2024). "Consequently, a higher expression of TIM-3+ on sTILs may inhibit this population’s capacity to shift to the intra-tumoral compartment and interact with the TIM-3-galectin-9 complex on the tumor cell surface, thus making the TIM-3-galectin-9 complex more prone to proteolytic shedding and secretion." (PMID 36672332, 2023). "However, the neutralization of LGALS9 alone failed to suppress the tumor in PDAC15." (PMID 37945567, 2023). "In addition to Galectin-9, several ligands capable of interacting with TIM-3 have been described but Galectin-9 is probably the most studied due to its broad expression in the tumor environment where it could promote inflammation or facilitate tumor escape." (PMID 32296421, 2020). "Therefore, the better survival of patients with high TIM-3 and LGALS9 expression observed in our study might be due to a better immune response in the tumor, regardless of the high expression of TIM-3." (PMID 31747929, 2019). "Low TPS results revealed significantly changed pathways involving tumour–non-cancerous cell interactions, such as PD-L1/PD-1 (CD274 on tumour cells and PDCD1 on T cells) and Galectin-9/TIM-3 (LGALS9 on tumour cells and HAVCR2 on immune cells)." (PMID 39457550, 2024). "Interestingly, our study found that there was certain expression of Galectin-9 in the terminally exhausted CD8+TILs in DLBCL, which might aggravate the exhaustion of CD8+TILs through TIM3/Galectin-9 pathway and further weaken the anti-tumor function of CD8+TILs." (PMID 38369502, 2024).
tumor (continued). "The expression levels of most immune suppressive genes in the tumor and inflammation areas of CSCC are not significantly higher than those in the non‐cancer samples, except for LGALS9 and IDO1." (PMID 35986392, 2022). "Not surprisingly, galectin-9, MHC class II and CD80 is present on a variety of cells in the tumor microenvironment including B cells, macrophages, DCs and monocytes." (PMID 25614821, 2015). "Considering that some of the described functions for galectin-9 require the integrity of the TCR/CD3 signaling pathway (such as calcium mobilization), these functions of galectin-9 may not be relevant in recently activated lymphocytes in tumor-draining lymph nodes." (PMID 34572756, 2021).
cancer (269 papers, 2009 to 2026). A tumor composed of atypical neoplastic, often pleomorphic cells that invade other tissues. "Galectin-1 and Galectin-3 modulate immune checkpoint pathways and cancer-associated fibroblast activation, whereas Galectin-9 interacts with TIM-3 to induce T-cell exhaustion." (PMID 42129932, 2026). "Galectin-9, encoded by the Lgals9 gene, is a ubiquitously expressed tandem-repeat galectin, known to exert numerous roles in cancer, infection, and inflammation." (PMID 40986321, 2025). "Among them, Galectin‐9 (LGALS9) has been implicated in various aspects of cancer biology, including immune evasion, angiogenesis and cell adhesion." (PMID 40534096, 2025). "The TIM3/Galectin-9 pathway is particularly relevant in the context of HPV-associated cancers, especially cervical cancer." (PMID 40282436, 2025). "Galectin‐9 (LGALS9), a β‐galactoside‐binding lectin, has been implicated in various aspects of cancer biology, including immune modulation and metastasis." (PMID 40534096, 2025). "We validated the results obtained for galectin-9, a glycoprotein of the galectin family encoded by the Lgals9 gene, recently identified as an immunosuppressive factor in cancer." (PMID 38195762, 2024). "Future studies are needed to precisely dissect the underlying molecular mechanisms in regulating ATXN3 and Galectin-9 expression under biological conditions versus cancer." (PMID 38815863, 2024). "Endogenous galectin-9 expression in cancers has been associated with cancer cell adhesion or metastasis." (PMID 37047155, 2023). "Increased galectin-9 levels have been observed in both viral and bacterial infections, and its association with autoimmune processes and cancer is also possible." (PMID 37189444, 2023). "Galectin-9 (Gal-9) causes the inactivation of various immune cells, such as natural killer (NK) cells and T cells, enabling cancer cells to evade from immunosurveillance." (PMID 37767098, 2023). "Future studies are needed to test the exact functions of galectin-9 under disease conditions, including deep venous thrombosis, cancer-associated thromboembolism, and thromboinflammation." (PMID 36873388, 2023). "A comprehensive investigation has revealed significant alterations in Galectin-9, encoded by the LGALS9, across various cancer types." (PMID 37858131, 2023). "Two meta-analyses reported that higher galectin-9 expression in solid cancer tissue is associated with improved cancer-specific survival (CSS) or overall survival (OS)." (PMID 36527024, 2022). "Galectin-9 (Gal-9) expression can be negatively or positively associated with cancer patient prognosis, depending on the cancer type." (PMID 34195077, 2021). "Functionally, Galectin-9 (Gal-9) has been implicated in regulating apoptosis in various types of cancer cells." (PMID 32486344, 2020). "This study uncovered a self-supporting biochemical mechanism underlying high levels of galectin-9 expression operated by the human cancer and embryonic cells employed in our investigations." (PMID 33295886, 2020). "The mutation rate of galectin-9 varied between 0 and 2.5% for different cancers according to the COSMIC database." (PMID 33178839, 2020). "The mechanism of this galectin-9-mediated cancer cell apoptosis is likely linked to the carbohydrate-recognition function because administration of lactose blocked its proapoptotic effect." (PMID 29389859, 2018). "This suggests that the upregulation of these genes, including PDCD1, TIGIT, and LGALS9, may be associated with a more favorable immune response and a lower risk of cancer progression or recurrence." (PMID 40747615, 2025). "For the first time, we showed that SNPs of the gene encoding galectin-9 could be associated with susceptibility to cancer." (PMID 36768365, 2023). "The high expression of LGALS9 is associated with the poor prognosis of many human cancers." (PMID 34660693, 2021).
cancer (continued). "Notably, our study displayed that patients with DLBCL harboured a higher frequency of mutations in galectin-9 as compared to those with other cancers." (PMID 33178839, 2020). "It remains to be determined whether splice variant-specific profiling has a similar benefit in other cancer types, including those in which overall galectin-9 expression is a prognostic marker." (PMID 25259711, 2014). "Galectin-9 encoded by LGALS9 could bind to receptor CD44 to regulate anti-cancer immunity." (PMID 38918785, 2024). "Galectin-9 may be a good diagnostic and prognostic marker for cancer staging." (PMID 37371482, 2023). "However, the biochemical mechanisms underlying increased galectin-9 expression in human cancer cells are unknown." (PMID 33295886, 2020). "More than 20 immunoinhibitory genes were differentially expressed among subclusters in BRCA, LGG, and SKCM, with LGALS9 differing in over 15 cancer types." (PMID 41150760, 2025). "Galectin-9 (Gal-9), a recently emerging target in cancer immunology, has gained increasing attention as a potential therapeutic agent." (PMID 40138336, 2025). "LGALS9, a member of the galectin family, is involved in cell adhesion and migration, processes that are crucial for cancer metastasis." (PMID 41411347, 2025). "Galectin-9 (Gal-9) has gained increasing attention in recent years in the field of cancer immunology." (PMID 40138336, 2025). "During acute immune responses, Tim-3 enhances NK cytotoxicity and IFN-γ production, while in chronic inflammation or cancer, its engagement—particularly by Galectin-9—suppresses NK activity and cytokine production, contributing to immune exhaustion." (PMID 40564995, 2025). "Beyond cancer, it has been observed that LGALS9 plays a role in bone-marrow-derived mesenchymal stem-cell-mediated immunosuppression." (PMID 40362421, 2025). "Our results support a TNBC model whereby in older cohorts, myeloid cells and CAFs interact with cancer basal cells via LGALS9/P4HB, PPIA/BSG and PLAU/PLAUR signaling to promote EMT and cell motility." (PMID 41188599, 2025). "When T cells are exhausted, blocking TIM-3 or altering the TIM-3/Galectin-9 connection has been demonstrated to restore T cell activity and improve immune responses in chronic viral infections and cancer models 78-81." (PMID 39664572, 2024). "It is noteworthy that Galectin 9 (Gal-9) and galectin 3 (Gal-3) can interact with PD-1 and thus are emerging targets for cancer immunotherapy in different combinations." (PMID 39507530, 2024). "Increased serum levels of galectin-9 was found in cancer patients and predicted poor response to treatment in high grade serous ovarian carcinoma and in adult leukemia patients." (PMID 38504978, 2024). "T cell immunoglobulin and mucin-domain containing-3 (Tim-3) and its ligand, galectin-9 (Gal-9), have been gaining increasing attention as potential targets for cancer and infectious disease immunotherapy." (PMID 39065812, 2024). "The reduction of ATXN3 results in the degradation of Galectin-9 protein, thereby impeding Galectin-9-induced apoptosis and promoting the progression of cancer." (PMID 38815863, 2024). "In the older TNBC cohort, myeloid cells and CAFs interact with cancer basal cells through LGALS9/P4HB, PPIA/BSG, and PLAU/PLAUR ligand/receptor pairs to promote EMT and cell motility, as confirmed by the age-related increase in EMT ARPs." (PMID 39483921, 2024). "Altogether, these studies suggested that depending on the disease context, galectin-9 can serve as a biomarker and therapeutic target in cancer." (PMID 36873388, 2023). "Altered galectin-9 expression has been reported in different types of cancers and is negatively correlated with overall survival (OS) in patients, making galectin-9 an interesting biomarker and potential target for immunotherapy." (PMID 36768365, 2023).
cancer (continued). "The high levels of endogenous galectin-9 increase the cellular adherence ratio to promote cancer cell aggregation, whereas reduced endogenous galectin-9 expression is related to cancer cell invasion and metastasis." (PMID 37047155, 2023). "Galectin-9 augmented an immunosuppression in TME via accelerating TRIM29-mediated degradation of STING in human cancers." (PMID 36733484, 2023). "Specifically, several immune checkpoints including TNFRSF18, TNFRSF4, VSIR, LGALS9, HAVCR2, and TNFRSF14 are significantly associated with RARA-AS1 in more than 10 types of cancer." (PMID 37833349, 2023). "Other immune checkpoint ligands, NECTIN2, LGALS3, and LGALS9 were highly expressed in cancer cells or other infiltrating cells." (PMID 36529697, 2023). "Galectin-9 is constitutively expressed in antigen-presenting cells and its expression is upregulated by interferons in cancer cells." (PMID 36873388, 2023). "The functions of extracellular galectin-9 (induction of apoptosis in inflammatory cells) and intracellular galectin-9 (induction of apoptosis in cancer cells) differ." (PMID 37047155, 2023). "For example, TME T cells induce galectin-9 secretion from tumor cells derived from various malignant tumors." (PMID 37275901, 2023). "The galectin-9 that is produced by cancer cells seems to work dynamically with the surrounding cells." (PMID 37371482, 2023). "High mobility group box 1 (HMGB1) has been demonstrated to induce the Toll-like receptor 4-mediated pathway to promote galectin-9 expression in cancer cells." (PMID 37371482, 2023). "Galectin-9 has several reported receptors notably present in both immune cells and cancer cells with T-cell immunoglobulin and mucin-domain containing-3 (TIM-3) being the most important and described one." (PMID 38098486, 2023). "The analysis of cellular communication with SC datasets showed that the L-R pairs of LGALS9 are highly abundant in the communication of the TAMs with mostly cancer cells, ductal cells, and TAMs themselves." (PMID 37945567, 2023). "LGALS9 encodes galectin-9, a tandem protein found to interact with PD-1 and TIM-3, regulating T-cell death and serving as a target for cancer immunotherapy." (PMID 37686016, 2023). "Previous studies suggested that the TIM-3-galectin-9 pathway can induce T-cell apoptosis and protect cancer cells against cytotoxic T-cell-induced death, which promotes immune escape." (PMID 37047155, 2023). "Our analysis revealed a positive association between the expression of P2RY6 and immunosuppressive genes such as CD86, CD80, IL2RA, TGFB1, and LGALS9 in pan-cancer." (PMID 37880703, 2023). "Other immune checkpoint ligands or receptors, SELPLG, HAVCR2, LGALS3, and LGALS9, were highly expressed in cancer cells or other infiltrating cells." (PMID 36529697, 2023). "PDL1, CD80/CD86, major histocompatibility complex class II (MHC II), CD155, and galectin-9 (GAL9) are some ligands expressed in cancer cells." (PMID 38022130, 2023). "The interactions of LGALS9 showed that TAMs used LGALS9 ligand to communicate with cancer cells, ductal cells, and tumor-suppressor immune cells." (PMID 37945567, 2023). "To date, GAL-9 has been mainly investigated in the context of tumorigenesis, with upregulation of LGALS9 expression in various cancer types having been reported." (PMID 38248876, 2023). "Galectin-9 in cancer cells combines with V-domain Ig-containing suppressor of T cell activation (VISTA, an immune checkpoint protein) to support the protumorigenic immunosuppressive TME." (PMID 37275901, 2023). "Using 90 surgically resected specimens, we measured galectin-9 mRNA expression in hepatocarcinoma and adjacent cancer tissue and found significant differences in terms of pathologic differentiation, TNM, and recurrent metastasis (p < 0.05)." (PMID 37047155, 2023). "The genes included in the high-expression group were VTCN1, CD200, CD276, and LGALS9, as they showed a higher expression level in all the cancer samples." (PMID 36157232, 2022).